SLAMF7 (SLAM family member 7)
Diseases named in the same sentence as SLAMF7 in open-access papers (continued):
Sharing a sentence is not in itself a finding about the gene and the disease.
tumor (continued). "In a preclinical study, a suicide gene was incorporated into anti-SLAMF7 CAR-T cells; the CAR-T cells eliminated SLAMF7-positive tumor cells in mice and were, themselves, eliminated when rimiducid was administered." (PMID 39272790, 2024). "In tumor cells with low SLAMF7 expression, using a CCR2 antagonist to inhibit the CCL2/CCR2 axis, generates a greater anti-tumor impact when combined with PD-1 antibody." (PMID 39223632, 2024). "Of these, SLAMF7/CS1, GPRC5D, CD138 and CD38 are showing different clinical success rates, while data for newer tumor antigens like CD70, NKG2DL and κ-light chain are to be expected." (PMID 38720898, 2024). "We also observed increased expression levels of immune‐related genes, such as SLAMF7, TNFSF8, BTN3A1, CD2, LGALS9, PRF1, and MX2, in tumor samples from the MT group of the Local‐SCLC cohort." (PMID 38125769, 2023). "Alternative MM antigens that are being explored as targets for CAR therapy are CD38, SLAMF7, and CD138; however, on-target off-tumor expression of these antigens on other hematopoietic or non-hematopoietic cells compromises their safety profile." (PMID 36850001, 2023). "As the same results obtained in mouse, they also confirmed that this dependence required SLAMF7 (CD319 or CRACC), a SLAM family member which expressed on macrophages and tumor cell targets in human cells." (PMID 36960057, 2023). "They showed that T cells expressing the SLAMF7-specific CAR accompanied with suicide-gene construct specifically identified and eradicated SLAMF7-positive cells in vitro and tumor cell-bearing mice." (PMID 34321099, 2021). "In the subsequent functional analyses with GRACE, we showed that both SLAMF7 and LTA were co-expressed in tumor samples consistent with the results by WGCNA." (PMID 33403041, 2021). "Double IHC staining showed a subset of T cells co‐expressed SLAMF7 in the engrafted tumor, without detectable CD20/SLAMF7 dual‐positive cells." (PMID 39877932, 2025). "The activity of UCARTCS1 was found to be independent of the proportion of tumor cells, the SLAMF7 expression level on MM cells, or the frequency of regulatory T-cells in MM bone marrow samples." (PMID 41228264, 2025). "Despite advancements in therapies targeting established antigens, such as BCMA, CD38, SLAMF7, and GPRC5D, specific challenges persist, including antigen escape, treatment resistance, and off-tumor toxicity, highlighting the urgent need for novel therapeutic modalities." (PMID 40597436, 2025). "It remains possible that, as with tumor cell elimination by macrophages, SLAMF7 downstream signaling during infection occurs without adaptor recruitment." (PMID 40231463, 2025). "As we have shown by CD8+ T cells from tumor-draining lymph nodes as well as from the peripheral blood of patients with advanced stages of HNSCC, engaging SLAMF7 is also able to enhance T-cell responses in a presumably immunocompromised environment, where T-cell function is downregulated." (PMID 40909279, 2025). "In the majority of MM patients, SLAMF7 mRNA and protein are expressed in CD138+ tumor cells." (PMID 37754488, 2023). "These cytotoxic cells express Eomes and GzmK together with uniquely high expression of the signaling lymphocytic activation molecule family member 7 (SLAMF7), a surface protein that was already described to characterize CD4+ T cells with cytotoxic potential in tumor and autoimmune diseases." (PMID 37965314, 2023). "It has been reported that anti-SLAMF7 CAR-T cells could eliminate the primary and MM tumor cell lines, as well as normal lymphocytes with significant expression of SLAMF7." (PMID 33781320, 2021). "In contrast, another report showed that SLAMF7 coexpression on macrophages and tumor cells is not required for CD47-mediated phagocytosis." (PMID 33597728, 2021).
tumor (continued). "The mRNA expression data prompted us to stain tumour sections to validate immune-related expression, by which we chose seven immunophenotypical markers [CD45, CD4, CD8, FOXP3, CD79A, Kappa/Lambda (K/L) and SLAMF7] to study both T cell and B cell expression." (PMID 32195184, 2020). "Therefore, our data suggest that SLAMF7 agonism sensitises CD8+ T cells to checkpoint inhibition, supporting a combinatorial strategy that could broaden the efficacy of checkpoint-based tumor immunotherapy." (PMID 40909279, 2025). "Given that hepatocyte TM4SF5 expression is specifically linked to SLAMF7 downregulation, we further explored whether TM4SF5 expression in NK cells might also lead to NK cell inactivation for tumor development, and how TSI treatment might recover the TM4SF5-mediated SLAMF7 downregulation." (PMID 39828766, 2025). "Further, targeting of SLAMF7 on CD8+ T cells could serve as a mean to regulate the formation of ICAM-1-LFA-1 dependent CTL populations within the tumor tissue, and by enrichment of tumor-specific CD8+ T cells, SLAMF7 signals could improve the tumor control." (PMID 39390117, 2025). "In this study, we demonstrated that SLAMF7 is highly expressed on activated DNT, and not only intrinsically enhances the cytotoxic function of DNT but also engages in homotypic ligand-receptor interactions with SLAMF7-expressing tumor cells, exerting dual effects on DNT antitumor immunity." (PMID 41168829, 2025). "In addition, DNT have been reported to effectively kill tumor cells through cytotoxic molecules secretion or NKG2D/NKG2DL pathway, we detected whether SLAMF7 is involved in the regulation of these molecules." (PMID 41168829, 2025). "Having identified the beneficial effects of SLAMF7 activation regarding CD8+ T-cell responses in polyclonal activating settings, it was investigated whether these results could be extended to CD8+ T-cell responses against viral and also tumor antigens." (PMID 40909279, 2025). "Importantly, SLAMF7 is not expressed in any other normal human tissue outside the haematopoietic system, which reduces concerns about off-tumour toxicity." (PMID 41228264, 2025). "This off-target effect could diminish anti-tumor immunity, particularly in patients who have not yet accumulated dysfunctional or suppressive SLAMF7+ CD8+ T cell subsets." (PMID 40909279, 2025). "In this study, we found that the levels of IL‐12 and SLAMF7 expressed by clinical tumor patients were not sufficient to regulate the tumor immunosuppressive microenvironment (TIME), as determined through analysis of clinical databases and the Human Protein Atlas." (PMID 39713206, 2024). "In addition, efficacy of UCARTCS1 was not affected by SLAMF7 expression level on MM cells, proportion of tumor cells, or frequency of regulatory T-cells in BM samples obtained from MM patients." (PMID 39060023, 2024). "On the other hand, SLAMF7 negative tumor cells could also be killed by the bystander effect of the activated macrophages nearby when agonistic anti-SLAMF7 antibodies were administered." (PMID 35525858, 2022). "In addition, “reactome immunoregulatory interactions between a lymphoid and a nonlymphoid cell” were upregulated in SLAMF7+ T cells (p = 0.001); this pathway regulates the response of T cells to self and tumor antigens." (PMID 33597728, 2021). "However, a number of anti-tumor antibodies target molecules expressed by tumor cells belonging to the hematopoietic lineage and, hence, also target their normal cell counterparts, notably lymphocytes (anti-CD20, -CD52, -CD38, SLAMF7, etc.)and myeloid cells (anti-CD30, -CD33, etc.)." (PMID 28855903, 2017). "To investigate whether SLAMF7 on DNT contributes to tumor cytotoxicity through this mechanism, we firstly assessed SLAMF7 expression in various tumor cell lines, which showed that A20 cells had the highest SLAMF7 expression, while CT26 cells had no SLAMF7 expression." (PMID 41168829, 2025).
tumor (continued). "BiTEs and hemibodies were next tested in T cell cultures in the absence of tumor cells, because we detected the substantial expression of CD38 and SLAMF7 on CD3 and CD8 T lymphocytes, albeit distinct T cell subpopulations expressed the antigens in a mutually exclusive pattern." (PMID 33420283, 2021).
cancer (48 papers, 2017 to 2026). A tumor composed of atypical neoplastic, often pleomorphic cells that invade other tissues. "Our findings present a new insight into the underlying antitumor mechanism of DNT and establish SLAMF7 as a new target for improving adoptive DNT-based cancer immunotherapy." (PMID 41168829, 2025). "However, in cancer-related contexts, SLAMF7 expression on CD8+ T cells is also associated with T cell exhaustion and a suppressive phenotype." (PMID 40909279, 2025). "In antigen-specific human models, SLAMF7 activation boosts CD8+ T-cell responses against the tumor-associated antigen NY-ESO-1, a key target in several cancers including HNSCC." (PMID 40909279, 2025). "NK cells are regulated through SLAMF7, which then plays a vital role in cancer recognition and antitumor responses." (PMID 37754488, 2023). "SLAMF7 appears to have both inhibitory and stimulatory effects in cancer, depending on the type of cancer and context in which it is expressed." (PMID 37251372, 2023). "SLAMF7 on macrophages interacts with integrin macrophage-1 antigen (MAC-1) on macrophages to promote the phagocytosis of cancer cells by macrophages." (PMID 36882399, 2023). "For example, Calreticulin and SLAMF7, are pro-phagocytic receptors that are found in a variety of malignancies but are minimally expressed on healthy cells." (PMID 35865547, 2022). "We have previously defined roles for SLAMF7 in a number of conditions including HIV infection and cancer, and have also worked to modulate SLAMF7 signaling for therapeutic benefit." (PMID 36199066, 2022). "Calreticulin expression is increased in a range of cancers, including leukemias, bladder cancer, and ovarian cancer, whereas SLAMF7 expression is increased in predominantly hematopoietic tumor cells." (PMID 35865547, 2022). "In terms of co-inhibitors, GMFG showed a positive relationship with PDCD1LG2 (PD-L2) and SLAMF7 in most cancers." (PMID 33863293, 2021). "In the current report, we aimed to further delineate the potential role of SLAMF7 expression on cancer cells for CD47-targeted and monoclonal antibody-based therapy in DLBCL." (PMID 30710089, 2019). "CD47 is a promising new target in cancer immunotherapy and recently the pro-phagocytic signal SLAMF7 has been shown to have a crucial role in phagocytosis induced by CD47-blocking antibody in hematological tumors." (PMID 30710089, 2019). "In this respect, expression of the pro-phagocytic signal SLAMF7 on both macrophages and cancer cells was recently reported to be a requisite for CD47 antibody-mediated phagocytosis." (PMID 30710089, 2019). "Specifically, macrophages obtained from SLAMF7 knock-out mice proved to be defective in phagocytosis of cancer cells." (PMID 30710089, 2019). "Further, SLAMF7 expression on hematopoietic cancer cells was reported as a requisite for phagocytosis upon treatment with a CD47 blocking antibody." (PMID 30710089, 2019). "In co-inhibitors, we found a relatively strong and positive relationship between PD-1 expression and SLAMF7 expression in some cancer types." (PMID 30607140, 2018). "Based on these results, modulating their function via SLAMF7 may represent a promising strategy for clinical cancer immunotherapy." (PMID 41168829, 2025). "SLAMF7 is upregulated in MM and plays a role in the proliferation of cancer cells." (PMID 37754488, 2023). "In some types of cancer, such as MM and breast cancer, SLAMF7 has been found to be overexpressed, and its presence on cancer cells might aid them evade attack by the immune system." (PMID 37251372, 2023). "Adoptive transfer of SLAMF7 CAR T cells into MM-bearing mice shows potent anti-cancer efficacy." (PMID 37251372, 2023). "Interestingly, data from The Cancer Genome Atlas RNA sequencing dataset showed a significant relationship between SLAMF7 positivity and better prognosis in melanoma and other cancers." (PMID 36159781, 2022).
cancer (continued). "The important corollary of these findings is that cancer cell expression of SLAMF7 does not associate with or predict for therapeutic effects of CD47-targeting drugs." (PMID 30710089, 2019). "Some of the significant cancer hallmark terms are inflammatory response (CD14, CD69, IL10RA), KRAS signaling up (CD37, IL10RA, GPNMB), IL-6/JAK/STAT3 signaling (CD14, CSF2RB), Interferon Gamma Response (CD69, CSF2RB, IL10RA, VCAM1, SLAMF7), TNF-alpha Signaling via NF-kB (CD69)." (PMID 35486660, 2022). "Our findings provide insights into the contextual role of SLAMF7 in CD8+ T cells and explore its potential as a target to modulate T-cell function for cancer immunotherapy." (PMID 40909279, 2025). "SLAMF7 enhances DNT antitumor activity through both ligand-independent and ligand-dependent dual patterns, which can be a potential target for improving cancer immunotherapy." (PMID 41168829, 2025). "SLAMF7 is a key regulator of DNT-mediated cytotoxicity and a promising target for improving DNT cell function in cancer therapy." (PMID 41168829, 2025). "Particularly of interest as an alternative cancer antigen for MM CAR-T cell therapy is CD2 subset 1 (CS1, CD319 or signaling lymphocytic activation molecule family member 7 [SLAMF7])." (PMID 38720898, 2024). "For example, TOP2A, LAG3, SLAMF7, and PTGS2 are established or promising key targets for cancer treatments and immunotherapy." (PMID 38746418, 2024). "TM4SF5 expression in cancer cells downregulated stimulatory ligands and receptors for NK cell cytotoxicity, including SLAMF6, SLAMF7, MICA/B, and others." (PMID 34921636, 2021). "Reversely, expression of the pro-phagocytic receptor SLAMF7 was reported to be crucial for execution of macrophage-mediated phagocytosis of cancer cells, although cancer cell-expression of SLAMF7 is not required for CD47 antibody treatment." (PMID 38116002, 2023). "In addition, we found that macrophage subpopulations (clusters 1, 5, 7, 8, and 9) from cancer tissues expressed a certain number of immunosuppressive genes, such as VEGFA, MMP14, MMP19, S100A2, APOE, HMOX1, SLAMF7, SIRPα, LAG3 and IL18." (PMID 36158683, 2022). "Macrophages may also recognise and clear haematopoietic cancer cells via SLAMF7 heterodimerising between cancer cells and macrophage, and activating CR3 on the macrophage, resulting in phagocytic clearance of the cancer cell." (PMID 34177884, 2021). "In conclusion, cancer cell expression of SLAMF7 is not required for phagocytosis and, in contrast to CD47 expression, should not be used as selection criterion for CD47-targeted therapy." (PMID 30710089, 2019). "Taken together, these data clearly demonstrate that expression of SLAMF7 on hematopoietic cancer cells is not required for phagocytosis by macrophages upon CD47 blocking therapy." (PMID 30710089, 2019). "Expression of SLAMF7 on cancer cells also did not impact on the in vitro phagocytic activity of macrophages upon treatment with the CD20 antibody rituximab alone, or in combination with CD47 antibody inhibrix." (PMID 30710089, 2019). "The data presented here demonstrate that surface expression of SLAMF7 on hematopoietic cancer cells, specifically on B cell malignant cells, is not required for phagocytosis upon CD47 blocking treatment, nor upon combination treatment with rituximab." (PMID 30710089, 2019). "Here, we demonstrate that in fact SLAMF7 expression on cancer cells is not required and does not impact on CD47 antibody therapy." (PMID 30710089, 2019). "Considering that SLAMF7 is a target in cancer therapy, its epigenetic regulation in Th1 cells and differential expression in IFN‐γ producing memory CD4+ T cells encouraged us to take a closer look at the SLAMF7 expression at the protein level in TCR‐triggered CD4+ T cells." (PMID 41187703, 2026).
cancer (continued). "Future studies will be necessary to profile SLAMF7 expression and metabolic programs in patient-derived DNT, and to evaluate whether the therapeutic mechanisms identified here are preserved or altered in cancer settings." (PMID 41168829, 2025). "Next, we evaluated whether phagocytic activity of a clinically relevant CD47 targeting antibody might similarly be independent of SLAMF7 expression on cancer cells." (PMID 30710089, 2019). "In conclusion, mRNA and/or protein expression levels of SLAMF7 on hematopoietic cancer cells should not be used as selection/exclusion criterion for future clinical studies that evaluate the therapeutic potential of CD47-blockade or the combination with CD47 blocking therapy." (PMID 30710089, 2019). "Thus, the effect of a clinically relevant CD47 blocking IgG4 antibody is mediated by blocking of the SIRPα/CD47 interaction and does not require expression of SLAMF7 on cancer cells." (PMID 30710089, 2019). "Thus, expression of SLAMF7 on cancer cells is not a requisite for phagocytosis upon CD47 antibody treatment." (PMID 30710089, 2019). "In this study, the authors demonstrate that SLAMF7 expressed by cancer cells is not required for phagocytosis suggesting that, in contrast to CD47 expression, SLAMF7 should not be used as selection criterion for CD47-targeted therapy." (PMID 30710089, 2019). "Thus, for all of the macrophage subtypes found in the TME of DLBCL, SLAMF7 expression on cancer cells is not required for anticancer activity upon CD47 targeting, with M2 macrophages appearing to respond more effectively to CD47-targeting than M1 macrophages while having lower SLAMF7 expression." (PMID 30710089, 2019).